OLIG2 (oligodendrocyte transcription factor 2)
Diseases named in the same sentence as OLIG2 in open-access papers (continued):
Sharing a sentence is not in itself a finding about the gene and the disease.
melanoma (continued). "In addition, downregulation of Olig2 suppressed migration and invasion of melanoma cells by inhibiting EMT." (PMID 33833342, 2021). "Our data provide the first evidence supporting the role of Olig2 in invasive growth of melanoma." (PMID 33833342, 2021). "We confirmed that Olig2 was overexpressed in melanoma cells and tissues." (PMID 33833342, 2021). "Treatment with PD98059 significantly suppressed expression of Olig2 and Snail in melanoma cells." (PMID 33833342, 2021). "Our findings suggest that Olig2 may be a novel potential regulator of melanoma progression." (PMID 33833342, 2021). "Furthermore, the expression level of MMP-1 was attenuated in Olig2 knockdown of melanoma cells." (PMID 33833342, 2021). "Here, we investigated whether Olig2 regulates melanoma progression." (PMID 33833342, 2021). "However, the role of Olig2 in melanoma is still not clearly understood." (PMID 33833342, 2021). "Therefore, we examined the wound healing assay after suppressing Olig2 expression to determine whether Olig2 is involved in melanoma migration." (PMID 33833342, 2021). "To investigate the function of Olig2 in melanoma progression, we used CRISPR/Cas9 to knockdown the Olig2 gene in A375 and 501mel metastatic melanoma cells." (PMID 33833342, 2021). "We further verified that Olig2 influences the expression of MMP-1, another MMP that is important for invasion and growth of melanoma." (PMID 33833342, 2021). "Moreover, Olig2 was involved in the downstream stages of MEK/ERK and PI3K/AKT, which are major signaling pathways in metastatic progression of melanoma." (PMID 33833342, 2021). "However, the role of Olig2 in melanoma is not well characterized." (PMID 33833342, 2021). "However, it appears that block of Olig2 and BRAF&MEK inhibition do not show a distinct synergistic effect in reducing the viability of melanoma cells." (PMID 33833342, 2021).
pilocytic astrocytoma (5 papers, 2015 to 2023). Pilocytic astrocytoma is a rare subtype of low-grade glioma of the central nervous system characterized by a well circumscribed, often cystic, brain tumor with a discrete mural nodule and long, hair-like projections that extend from the neoplastic astrocytes. "Furthermore, pilocytic astrocytomas are generally diffusely positive for OLIG2 and SOX10, whereas in this case OLIG2 and SOX10 expression was seen in only a subset of cells." (PMID 35484611, 2022).
autism (4 papers, 2013 to 2023). Persistent deficits in social interaction and communication and interaction as well as a markedly restricted repertoire of activity and interest as well as repetitive patterns of behavior. "Surprisingly, only Olig2-Cre driven Anks1b conditional mutant mice had social deficits, suggesting a significant contribution of oligodendrocyte dysfunction to autism-like features in ANDS." (PMID 38129387, 2023). "In addition, the mRNA levels of brain development‐related genes CHD7 and oligodendrocyte development‐related genes Olig2 and MBP were significantly decreased in the VPA‐induced autism model group (p < 0.01), and improved after AVP treatment (p < 0.01)." (PMID 36239083, 2022).
depression (4 papers, 2012 to 2022). "Similarly, temporal lobe Olig2 expression is downregulated in major depressive disorder whereas antidepressant treatment preventing anhedonia in rodents upregulates Nfib in the frontal cortex following chronic mild stress." (PMID 28200020, 2017).
embryonal tumors (4 papers, 2024). "Medulloblastomas and other embryonal tumors are less common in older children and can be excluded by testing for OLIG2 negativity." (PMID 39440342, 2024). "They comprise a well-defined methylation cluster separate from other embryonal tumors and should therefore be considered in young children with small round cell tumors that do not match any known tumor classes; most tumors are synaptophysin and OLIG2 positive." (PMID 38500181, 2024). "Embryonal tumors with multilayered rosettes (ETMRs) which otherwise lack rosettes, a medulloepithelioma component, and neurocytic/neuropil-rich areas could also resemble embryonal tumors with BRD4::LEUTX fusions, but they are generally negative for OLIG2 and positive for LIN28A." (PMID 38500181, 2024).
glioneuronal tumors (4 papers, 2020 to 2023). "Looking in a supervised way at expression of particular differentiation markers commonly used for immunohistochemical analysis of glial/glioneuronal tumors, we found low GFAP expression, and modest levels of OLIG2, NeuN (RBFOX3), MAP2 and synaptophysin (SYP)." (PMID 34417833, 2021).
leukemia (4 papers, 2017 to 2025). A malignant (clonal) hematologic disorder, involving hematopoietic stem cells and characterized by the presence of primitive or atypical myeloid or lymphoid cells in the bone marrow and the blood. "In leukemia, Olig2 seems only oncogenic in thymocytes and collaborative with LMO1 and Notch1 to induce highly penetrant leukemia." (PMID 36990974, 2023). "For example, oligodendrocyte transcription factor (OLIG2) has a known role in both leukemia and in lymphatic diseases, which have a phenotypic similarity of 0.6." (PMID 28549478, 2017). "Interestingly, upregulation of Olig2 alone is weakly oncogenic in leukemia, however, together with LMO1 and Notch1, overexpression results in cell proliferation." (PMID 37274223, 2023). "OLIG2 was part of the SeedPS of leukemia; however, it was not part of the LCC that served as SeedPS in lymphatic diseases." (PMID 28549478, 2017).
lung carcinoma (4 papers, 2012 to 2023). "Simultaneously, previous results demonstrated Olig2 regulated lung cancer cell stemness by promoting CD133 transcription." (PMID 36990974, 2023). "In this article, we discovered that Olig2 was significantly overexpressed in lung cancer, regulated lung cancer metastasis and cancer stemness properties." (PMID 36990974, 2023). "Here in this article, we demonstrated Olig2 was highly expressed in lung cancer and contributed to lung cancer cell stemness by regulating CD133 transcription." (PMID 36990974, 2023). "Taken together, all these findings suggested that ACT001 regulates lung cancer stemness by reducing Olig2 levels to eventually decrease CD133 expression." (PMID 36990974, 2023). "In order to determine the effects of Olig2 on lung cancer stemness, transwell assay, and tumorsphere formation assay were performed after Olig2 knockdown or overexpression." (PMID 36990974, 2023). "The results suggested that the protein level of Olig2 was significantly increased in lung cancer relative to non-lung cancer specimens." (PMID 36990974, 2023). "All these findings suggested that Olig2 promoted lung cancer cell stemness and regulated CD133 production." (PMID 36990974, 2023). "In this article, we discovered Olig2 was overexpressed in clinical lung cancer tissues and acted as a transcription factor to regulate cancer stemness by regulating CD133 gene transcription." (PMID 36990974, 2023). "To discover the mechanism of Olig2 in regulating lung cancer stemness, we found that Olig2 acted as a transcription factor to regulate CD133 expression by directly binding to the CD133 promoter." (PMID 36990974, 2023). "Furthermore, the expression of CD133 was significantly decreased after Olig2 knock down with siRNA and increased after Olig2 overexpression with pCMV-N-Flag-Olig2 vector which suggested Olig2 promoted lung cancer cell stemness by regulating CD133 expression." (PMID 36990974, 2023). "Moreover, to further reveal the effect of Olig2 on lung cancer stemness properties in vivo, immunohistochemical and western blot assay were performed to detect stemness markers including CD133, Nanog and Oct4 expression." (PMID 36990974, 2023). "Furthermore, we used pulmonary metastasis model and subcutaneous xenografts model to evaluate the effect of Olig2 on lung cancer cell stemness in vivo." (PMID 36990974, 2023). "Taken together, these results indicated that Olig2 was significantly overexpressed in lung cancer." (PMID 36990974, 2023). "Combined all information, we speculated that ACT001 may regulate lung cancer stemness through inhibiting Olig2 level to eventually decrease CD133 expression." (PMID 36990974, 2023). "However, the expression and the mechanism of Olig2 in cancer cell stemness in lung cancer is still unknow." (PMID 36990974, 2023). "To verify whether Olig2 regulates CD133 transcription in lung cancer, we cloned the CD133 promoter sequence into the pGL3 basic luciferase reporter vector and evaluated whether Olig2 could regulate CD133 promoter activity in A549 and NCI-H820 cells." (PMID 36990974, 2023). "Therefore, all these results suggested Olig2 promoted lung cancer stemness in vivo." (PMID 36990974, 2023). "On the basis of this analysis, we wondered whether Olig2 could regulate lung cancer stemness." (PMID 36990974, 2023). "However, the expression and function of Olig2 in lung cancer and LSCSs are still unknown." (PMID 36990974, 2023). "Altogether, these results indicated that ACT001 directly bound to Olig2 protein and promoted Olig2 degradation via ubiquitin proteasome pathway and eventually regulate lung cancer stemness marker CD133 transcription in lung cancer." (PMID 36990974, 2023). "The results suggested that ACT001 directly bound to Olig2 protein, induced Olig2 ubiquitination degradation, and inhibit CD133 promoter activity to decrease Olig2 and CD133 protein level in lung cancer." (PMID 36990974, 2023).
lung carcinoma (continued). "The immunohistochemical staining and western blotting results indicated that CD133 was obviously increased in lung cancer tissues compared to non-lung cancer tissues which were consistent with Olig2 expression." (PMID 36990974, 2023). "All these results suggested that Olig2 could be an excellent druggable target in anti-LCSCs therapy and lay a foundation for the further application of ACT001 in the treatment of lung cancer in clinical." (PMID 36990974, 2023). "Statistical result indicated Olig2 was highly expressed in lung cancer tissues compared with that in non-lung cancer tissues." (PMID 36990974, 2023). "The results indicated that Olig2 knockdown significantly inhibited A549 and NCI-H820 cell migration and tumorsphere formation while Olig2 overexpression clearly increased A549 and NCI-H820 migration and tumorsphere formation which suggested Olig2 promoted lung cancer stemness." (PMID 36990974, 2023).
multiple sclerosis (4 papers, 2012 to 2021). A progressive autoimmune disorder affecting the central nervous system resulting in demyelination. "In support of our conclusions of SVZ-derived increased oligodendrogenesis, it has been reported that during multiple sclerosis PSA-NCAM+/Sox10+/Olig2+ triple-positive cells are detectable in the white matter of periventricular lesions in post-mortem human brain tissue." (PMID 22892385, 2012).
brain injuries (3 papers, 2015 to 2024). "In traumatic brain injury, OLIG2 is upregulated immediately after injury and remains upregulated for up to 3 months, aiding in the remyelination of the tissue 71,72." (PMID 38559066, 2024).
brainstem gliomas (3 papers, 2020 to 2023). "Olig2 is expressed in 70–80% of diffuse intrinsic pontine gliomas (DIPG), a pediatric aggressive brainstem glioma, and regarded as an important transcription factor in gliomagenesis." (PMID 32160197, 2020).
central neurocytoma (3 papers, 2013 to 2015). A benign brain tumor composed of neural elements which most often arise from the SEPTUM PELLUCIDUM and the walls of the lateral ventricles. "Therefore, if tumor cells are positive for Olig2, it is inappropriate to consider the tumor as a neurocytoma." (PMID 24179531, 2013).
diffuse intrinsic pontine glioma (3 papers, 2013 to 2022). A neuroglial tumor that arises from the middle portion of the brain stem. "The authors also showed that the BMP4 treatment of diffuse intrinsic pontine glioma (DIPG) cells induced a stemness blockade accompanied by decreased SOX2 and OLIG2 expression, further validating our findings." (PMID 36497175, 2022).
experimental autoimmune encephalomyelitis (3 papers, 2008 to 2016). An autoimmune demyelinating disease of the central nervous system that is produced experimentally in animals by the injection of homogenized brain or spinal cord in Freund's adjuvant. "NogoA+ mature oligodendrocytes and Olig2+ oligodendrocyte precursor cells were examined in SCD in patients with early and chronic MS, normal-appearing MS cortex, and control cortex as well as in the rat model of repeated targeted cortical experimental autoimmune encephalomyelitis (EAE)." (PMID 24563023, 2014).
ischemic stroke (3 papers, 2019 to 2022). A stroke disorder caused by obstruction of blood flow to the brain, due to thrombotic (local blood clot formation) or embolic (due to a blood clot or other material traveling from another site) event. "We strongly believe that Olig2-OPC transplantation rescued learning and memory loss partially by enhancing the remyelination process in rats with ischemic stroke." (PMID 35547747, 2022). "Olig2-induced NG2+ OPCs (Olig2-OPCs) were then evaluated for their therapeutic potential in cell-based therapy for ischemic stroke." (PMID 35547747, 2022). "We then focused on the functional assessment of Olig2-OPCs and demonstrated their in vivo therapeutic potential in rats with ischemic stroke." (PMID 35547747, 2022). "To investigate the potential therapeutic benefit of Olig2-OPCs, we used a transient middle cerebral artery occlusion (tMCAO) rat model of ischemic stroke, Olig2-OPCs, and control-OPCs were frozen, thawed, and allowed to recover for 24-48 h before transplantation." (PMID 35547747, 2022). "Additionally, Olig2-OPC transplantation was further used to evaluate the efficacy against ischemic stroke." (PMID 35547747, 2022). "Thus, Olig2-OPC transplantation might represent an ideal cell resource for cell-based therapy for ischemic stroke." (PMID 35547747, 2022). "In summary, Olig2-OPC transplantation efficiently promoted myelination, resulting in recovery of learning and memory defects in rats with ischemic stroke." (PMID 35547747, 2022). "To further examine whether Olig2-OPC transplantation could improve spatial learning and memory in rats with ischemic stroke, we utilized the Morris water maze to examine learning and memory at 8 weeks after tMCAO." (PMID 35547747, 2022).
tauopathy (3 papers, 2020 to 2025). Neurodegenerative disorders involving deposition of abnormal tau protein isoforms (tau proteins) in neurons and glial cells in the brain. "Immunostaining confirmed a significant loss of OLIG2-positive cells and MBP-positive myelinated neurites in the hippocampus of tauopathy mice." (PMID 41331787, 2025).
anaplastic oligodendroglioma (2 papers, 2020 to 2021). A WHO grade III oligodendroglioma with focal or diffuse malignant morphologic features (prominent nuclear pleomorphism, mitoses, and increased cellularity). "The oligodendrocyte lineage gene Olig-2 was highly expressed in all diffuse gliomas, but higher Olig-2 in anaplastic oligodendrogliomas and GBM 12,13." (PMID 33391433, 2021).
Anxiety (2 papers, 2015 to 2023). Intense feelings of nervousness, tension, or panic often arise in response to interpersonal stresses. "Results were mixed as Olig2-Het and Olig2-KO mice spent more time in the open arms of the elevated plus maze (decreased anxiety) but covered less distance in the open arms (increased anxiety)." (PMID 38129387, 2023). "Moreover, juvenile Olig2 cKO mice exhibited anxiety-like behaviors and impairment in behavioral inhibition." (PMID 26696827, 2015). "It is conceivable that OL defects in Olig2 cKO mice could also affect the function of other neuronal cell types in addition to glutamatergic pyramidal neurons, which could contribute to the anxiety-like behaviors we observed in this study." (PMID 26696827, 2015). "Moreover, juvenile Olig2 cKO mice displayed anxiety-related behaviors." (PMID 26696827, 2015). "Moreover, juvenile Olig2 cKO mice showed anxiety and impulsivity-like behaviors." (PMID 26696827, 2015). "Furthermore, Olig2 cKO mice display anxiety-related maladaptive behaviors." (PMID 26696827, 2015).
astroblastoma (2 papers, 2021 to 2023). "Other tumors also traditionally called astroblastomas more highly express OLIG2, GFAP, ALDH1L1, and S100 β astrocyte genes and exhibit histomorphologic and patient demographic characteristics more closely matching original descriptions of astroblastoma." (PMID 36604386, 2023). "First, we confirmed the diagnosis by histopathological review including immunohistochemistry for EMA as well as Olig2, with the latter being partly positive only in both astroblastoma-like cases." (PMID 33481105, 2021).
autism spectrum disorder (2 papers, 2019 to 2021). A spectrum of developmental disorders that includes autism, and Asperger syndrome. "Recently, Olig2 overexpression was implicated in neurodevelopmental disorders down syndrome (DS) and autism spectrum disorder (ASD) but its influence on cognitive and intellectual defects remains unknown." (PMID 33859549, 2021). "Interestingly, OLIG2+ szDEGs are enriched for genetic variants associated with bipolar disorder and autism spectrum disorders, indicating potential cell type-specific relationship between genetic variants and disease-associated variation of gene expression." (PMID 31288836, 2019).
diffuse midline glioma (2 papers, 2017 to 2021). A diffuse glioma that arises from the midline structures of the central nervous system. "GPR17 clustering is associated with the overexpression of transcription factors such as Olig1 and Olig2 in pediatric diffuse midline glioma (pDMG), with the aborted differentiation of the oligodendrocytic lineage of the cells." (PMID 34359676, 2021).
ependymal neoplasms (2 papers, 2021 to 2024). "Expression of particular markers differentially expressed in astrocytic and in ependymal neoplasms revealed low OLIG2 and SOX10 expression (adjusted p = 3.89e − 26 and adjusted p = 7.75e − 65) within the novel group, with similar expression of GFAP (online resource)." (PMID 34355256, 2021). "Our case was classified as a subependymoma because it did not express Olig2 and SOX10 markers, which are absent in ependymal tumors." (PMID 38581034, 2024).
epilepsy (2 papers, 2021). A brain disorder characterized by episodes of abnormally increased neuronal discharge resulting in transient episodes of sensory or motor neurological dysfunction, or psychic dysfunction. "In our study, epilepsy was found in FGF9 knockout in Olig1-postive progenitors rather than in Olig2-postive progenitors, which regulates the sequential specification of neural progenitor cells into motor neurons and oligodendrocyte precursor cells." (PMID 33608505, 2021).
glaucoma (2 papers, 2022 to 2024). Increased pressure in the eyeball due to obstruction of the outflow of aqueous humor. "In an analysis of gene expression in a microbead induced ocular hypertensive model of glaucoma, Keuthan and colleagues found that Olig2 gene expression was significantly decreased by three days post microbead injection." (PMID 39191397, 2024). "For example, Olig2 fluorescence intensity was significantly diminished in glaucoma patients, and was positively correlated with MBP intensity." (PMID 39191397, 2024). "Interestingly, although mRNA expression levels of Olig2 were downregulated in all three glaucoma groups, the number of oligodendrocytes was lower only in WT+ONA optic nerves." (PMID 36733392, 2022).